ZKSCAN3 (zinc finger with KRAB and SCAN domains 3)
Diseases named in the same sentence as ZKSCAN3 in open-access papers (continued):
Sharing a sentence is not in itself a finding about the gene and the disease.
tumor (continued). "miR-124 is widely recognized for its role in suppressing epithelial-mesenchymal transition (EMT) and maintaining epithelial integrity, and its targeting of ZKSCAN3 implies a mechanism by which it can inhibit tumor progression and metastasis by reducing ZKSCAN3-mediated oncogenic activities." (PMID 39519085, 2024). "Furthermore, we underscore the clinical relevance of ZKSCAN3 and its potential implications for tumor prognosis and therapeutic strategies." (PMID 39519085, 2024). "Consequently, ZKSCAN3 emerges as a promising prognostic marker, and targeting its inhibition represents a potential strategy for anti-tumor therapy." (PMID 39519085, 2024). "ZKSCAN3, therefore, modulates the expression of multiple genes that facilitate tumor progression." (PMID 39519085, 2024). "In summary, we have characterized a previously unknown function of CHD1L in regulating tumor migration via ZKSCAN3-mediated autophagy in HCC." (PMID 34654797, 2021). "We proved that the CHD1L/ZKSCAN3 axis was important in cell autophagy-induced HCC tumor migration." (PMID 34654797, 2021). "The findings in some of these studies have additionally suggested that ZKSCAN3 could modulate several molecules known to play a key role in tumorigenesis and/or tumor progression, such as cyclin D1/D2, EGF, IGF-2, integrin-β4, MMP2/MMP9, NF-κB, and VEGF." (PMID 32824199, 2020). "In addition, ZKSCAN3-shRNA expression considerably retarded tumor formation as well as its subsequent growth in xenograft-bearing mice." (PMID 27447553, 2016). "In addition, ZKSCAN3 drives tumor invasion through NF-κB and MMP pathways." (PMID 40723888, 2025). "ZKSCAN3 plays a pivotal role in promoting tumor growth by modulating various cancer-related characteristics, including enhancing tumor cell proliferation, inhibiting apoptosis, facilitating invasion and metastasis, as well as suppressing autophagy in tumor cells." (PMID 39519085, 2024). "Therefore, ZKSCAN3 promotes the tumour progression, invasion, and migration and cell growth." (PMID 35600335, 2022). "Furthermore, removing ZKSCAN3 synergizes with TFEB expression in tumor inhibition." (PMID 30979895, 2019). "Using a quantitative RT-PCR method, we then assessed the effects of ZKSCAN3 silencing on the expression of matrix metalloproteinases (MMPs) that are known to play a critical role in cancer cell migration/invasion, angiogenesis, and resultant tumor progression and metastasis." (PMID 27447553, 2016). "Thus, ZKSCAN3 was likely to promote bladder tumorigenesis and tumor progression." (PMID 27447553, 2016). "ZKSCAN3, a transcription factor in the same family as ZKSCAN5, plays a role in many types of tumours." (PMID 35600335, 2022). "Further exploration demonstrated that the enhanced tumor cell migration and metastasis induced by CHD1L was mediated through ZKSCAN3-induced autophagic degradation of Paxillin." (PMID 34654797, 2021). "Hererin, we provided new evidences that CHD1L can specifically bind to the distal promoter region of ZKSCAN3 and negatively regulates its transcription, which further affects HCC tumor cell autophagy." (PMID 34654797, 2021). "Within the tumor microenvironment (TME), changes such as hypoxia and nutrient deprivation impose selective pressures on cancer cells that drive adaptation mechanisms potentially contributing to ZKSCAN3 dysregulation." (PMID 39519085, 2024). "The mechanisms for the upregulation of REV7 in tumor tissues have not been fully elucidated, although zinc finger protein with KRAB and SCAN domains 3 (ZKSCAN3), an oncogenic transcription factor, acts as a transcriptional repressor of REV7 in cultured tumor cells." (PMID 36980607, 2023). "The autophagy suppressive role of ZKSCAN3 may be limited to tumor cells as no apparent abnormality in autophagy was seen in ZKSCAN3-null mice." (PMID 41393507, 2025).
tumor (continued). "Previous studies have suggested that ZKSCAN3 directly or indirectly regulates the expression of various genes, such as CCND1, CCND2, EGFR, IGF-2, integrin-β4, NF-κB, and VEGF, all of which are known to involve tumorigenesis, tumor progression, and/or metastasis." (PMID 27447553, 2016). "Furthermore, Zkscan3 knockout mice display no discernable autophagy-related phenotypes, suggesting that there may be substantial differences in the regulation of autophagy between normal tissues and tumor cell lines." (PMID 32541927, 2020).
cancer (15 papers, 2016 to 2025). A tumor composed of atypical neoplastic, often pleomorphic cells that invade other tissues. "Recent studies have implicated ZKSCAN3 in oncogenesis, highlighting its potential utility as both a biomarker and a therapeutic target in cancer." (PMID 39519085, 2024). "While the precise molecular mechanisms underlying ZKSCAN3’s role in cancer remain elusive, its upregulated expression is linked to multiple downstream signaling pathways." (PMID 39519085, 2024). "A distinct study on CRC unveiled an association between the expression of ZKSCAN3 and the concentrations of cancer-related proteins, notably carcinoembryonic antigen (CEA), VEGF, and AKT, within liver metastases." (PMID 39519085, 2024). "Herein, we found that the ZKSCAN3 KO resulted in significant changes in the expression of many genes associated with angiogenesis and cancer pathways, further demonstrating the important roles of ZKSCAN3 in cancer progression." (PMID 37175493, 2023). "Aberrant expression of ZKSCAN3 has been shown to be associated with enhanced cell proliferation and cancer metastasis, although the exact role of ZKSCAN3 dysregulation in tumorigenesis remains to be defined." (PMID 35779634, 2022). "ZKSCAN3 is continuously upregulated in most human cancers; however, little is known about the mechanism underlying this upregulation." (PMID 36012568, 2022). "The ZKSCAN3 gene undergoes alternative splicing, giving rise to multiple transcript variants that encode distinct protein isoforms, each potentially possessing distinctive functional attributes within cancer cells." (PMID 39519085, 2024). "The chromosomal instability caused by ZKSCAN3 deficiency may have long-term impact on cancer formation and progression." (PMID 35779634, 2022). "However, the molecular mechanisms underlying cancer development/progression in response to ZKSCAN3 overexpression and its downstream signaling molecules are yet to be elucidated." (PMID 36012568, 2022). "In addition, ZKSCAN3 has recently been implicated in the regulation of autophagy whose defects are also linked to cancer." (PMID 27447553, 2016). "Additionally, the existence of distinct ZKSCAN3 isoforms could affect the responsiveness of cancer cells to targeted therapies, as some variants may confer resistance or sensitivity to specific treatments." (PMID 39519085, 2024). "Although ZKSCAN3 is proposed as a potential therapeutic target for various diseases, particularly cancer, direct small-molecule inhibitors targeting ZKSCAN3 are currently unavailable." (PMID 40723888, 2025). "In summary, past studies have revealed that ZKSCAN3 has a cancer-specific function and regulates the expression of cancer-related genes in a cancer type-specific manner." (PMID 41393507, 2025). "The analysis showed that ZKSCAN3 protein levels were higher in cancer samples at a statistically significant (p = 0.02) level." (PMID 41393507, 2025). "This review synthesizes current knowledge on ZKSCAN3’s regulatory networks and functional plasticity, emphasizing emerging themes in autophagy, cancer biology, and metabolic regulation." (PMID 40723888, 2025). "Comprehending the regulatory mechanisms governing ZKSCAN3 expression is of crucial importance for deciphering its role in cancer." (PMID 39519085, 2024). "The upregulation of ZKSCAN3 in response to c-Myc and NF-kB not only emphasizes its role in facilitating aggressive cancer phenotypes but also highlights its potential as a therapeutic target." (PMID 39519085, 2024). "We emphasize the clinical significance of ZKSCAN3, highlighting its potential as a biomarker for predicting cancer outcomes and its promise as an innovative therapeutic strategy for cancer treatment." (PMID 39519085, 2024). "The downregulation of ZKSCAN3 by these miRNAs occurs predominantly in specific cancer types and stages, highlighting a context-dependent regulatory framework that maintains the balance of ZKSCAN3’s oncogenic functions." (PMID 39519085, 2024).
cancer (continued). "ZKSCAN3 (also known as ZNF306) plays a pivotal role in the regulation of various cellular processes that are fundamental to the development of cancer." (PMID 39519085, 2024). "Nevertheless, the expression patterns and regulatory mechanisms of ZKSCAN3 across different human cancer types remain to be clarified." (PMID 39519085, 2024). "ZKSCAN3 (ZNF306) is a zinc finger transcription factor that plays a pivotal role in cancer progression by modulating multiple hallmarks of the disease." (PMID 39519085, 2024). "ZKSCAN3 belongs to a family of transcriptional repressor proteins and has been proved to play an essential role in cancer progression via different ways." (PMID 37175493, 2023). "Based on acute knockdown studies of cultured human cancer cells, ZKSCAN3 has been reported to transcriptionally regulate the expression of dozens of genes encoding proteins involved in various steps of autophagy and lysosomal biogenesis." (PMID 37175493, 2023). "This is in line with our qRT-PCR data investigating the ZKSCAN3 mRNA expression in normal colon total RNA and in the cancer-derived cell lines." (PMID 36986600, 2023). "Notable ZKSCAN3 overexpression is observed in the late stages of cancer or advanced cases with lymph node metastasis, indicating that ZKSCAN3 acts as a progression factor for malignant tumors." (PMID 36012568, 2022). "The identification of novel functions of ZKSCAN3 in fork processing and genome maintenance has expanded its physiological functions and shed new light on its cancer relevance." (PMID 35779634, 2022). "Zkscan3 and its gene, Zkscan3, has been reported to promote cancer cell proliferation, migration, and invasion by upregulating the expression of genes associated with cell cycle, cell proliferation, migration, angiogenesis, and proteolysis." (PMID 34940950, 2022). "ZKSCAN3 enhances the expression of a variety of target genes involved in cancer cell proliferation (cyclin D2), growth (IGF-2, integrin β4), metastasis (MMP26), and angiogenesis (VEGF)." (PMID 36012568, 2022). "We also examined the effects of ZKSCAN3 depletion on the sensitivity of BRCA1-deficient cells to Olaparib and cisplatin, both of which are used to treat BRCA1-deficient cancers." (PMID 35779634, 2022). "In other cancer types, the involvement of ZKSCAN3 in modulating cell proliferation/apoptosis and tumorigenicity has also been documented." (PMID 32824199, 2020). "The overall survival period and disease-free period were significantly shorter in cancers with high-grade ZKSCAN3 than in those with low grade tumors (p = 0.001 and 0.002, respectively, Student t-test)." (PMID 30241382, 2018). "Collectively, these results suggest that ZKSCAN3 modulates the expression of genes favoring cancer progression." (PMID 30241382, 2018). "However, the presence of high methylation, along with evidence of ZKSCAN3 overexpression in other cancer contexts, indicates that the regulatory control of ZKSCAN3 is multifaceted." (PMID 39519085, 2024). "The regulation of epigenetic modifications by ZKSCAN3 is stated as follows: The promoter region of the ZKSCAN3 gene demonstrates high levels of methylation in certain cancer types, highlighting a sophisticated regulatory landscape that encompasses both activation and repression mechanisms." (PMID 39519085, 2024). "Moreover, ZKSCAN3 modulates cell proliferation, apoptosis, and tumorigenicity in several cancer types." (PMID 39519085, 2024). "Notably, suppressing ZKSCAN3 halts cancer cell progression through the G0/G1 phase by inhibiting the Wnt/β-catenin signaling pathway." (PMID 39519085, 2024). "Notably, ZKSCAN3 represses autophagy-related genes, enabling cancer cells to survive under metabolic stress by preventing the degradation of essential cellular components." (PMID 39519085, 2024). "Such complexity emphasizes the necessity of a nuanced understanding of ZKSCAN3 regulation, as it may vary significantly between different cancer types and stages." (PMID 39519085, 2024).
cancer (continued). "In the context of ZKSCAN3, hypermethylation of its promoter in specific cancers implies a potential mechanism for downregulating its expression, which might be necessary to modulate its oncogenic functions under certain conditions." (PMID 39519085, 2024). "Furthermore, ZKSCAN3 expression correlates with cancer-related proteins like CEA, VEGF, and AKT levels in liver metastasis, with CEA further augmenting the invasive nature of ZKSCAN3-overexpressing cells." (PMID 39519085, 2024). "ZKSCAN3 may act differently in different cells; it may be involved in cancer progression and aging processes, but the mechanisms need further elucidation." (PMID 37175493, 2023). "Although we know that ZKSCAN3 is involved in the progression of many cancers, the mechanisms by which it affects cancer progression are still unknown or controversial, and therefore need further investigation." (PMID 37175493, 2023). "In addition to promoting cancer progression, ZKSCAN3 has also been reported to play an important role in inhibiting the transcription of autophagic and lysosomal genes, and cellular senescence." (PMID 37175493, 2023). "As a member of the zinc finger family DNA-binding proteins, ZKSCAN3 has been reported to function as a transcriptional repressor of autophagy, silencing of which can induce autophagy and promote lysosomal biogenesis in cancer cells." (PMID 37175493, 2023). "Increased gene copy numbers of ZKSCAN3 play a crucial role in ZKSCAN3 upregulation in cancers." (PMID 36012568, 2022). "ZKSCAN3 exhibits typical features of an oncogene in many cancer models." (PMID 33672287, 2021). "Although the exact molecular mechanisms conferring ZKSCAN3 function in cancer remain unclear, several downstream signaling pathways were associated with its high expression." (PMID 33672287, 2021). "Interestingly, knockdown of ZKSCAN3 in a variety of cancer cells resulted in induction of senescence." (PMID 34685484, 2021). "Furthermore, ZKSCAN3 was shown to increase cancer cell viability, migration, invasiveness, and in vivo tumorigenicity in prostate, bladder, and breast cancer models." (PMID 33672287, 2021). "Thus, the positive rates or levels of ZKSCAN3 expression were significantly higher in carcinoma than in benign prostate tissue or HGPIN and in HGPIN than in benign tissue." (PMID 32824199, 2020). "Moreover, our in vitro study demonstrated that ZKSCAN3 overexpression promoted the invasion ability of cancer cells." (PMID 30241382, 2018). "In this set of tissue specimens, strong (3+) ZKSCAN3 expression was detected in 12 (19.7%) of 61 low-grade carcinomas vs. 45 (45.9%) of 98 high-grade carcinomas (P=0.001) as well as in 18 (26.9%) of 67 non-muscle-invasive tumors vs. 39 (42.4%) of 92 muscle-invasive tumors (P=0.047)." (PMID 27447553, 2016). "Moreover, ZKSCAN3 expressed in stromal cells within the TME may be particularly vulnerable to dysregulation due to paracrine signaling from cancer cells." (PMID 39519085, 2024). "Furthermore, investigations have disclosed the presence of multiple alternative splicing isoforms of ZKSCAN3, which may exert disparate functional implications in cancer cells." (PMID 39519085, 2024). "Notably, ZKSCAN3 exhibits oncogenic properties across different cancer models." (PMID 39519085, 2024). "This miRNA-mediated control of ZKSCAN3 not only emphasizes the complexity of gene regulation in cancer but also presents potential therapeutic approaches where restoring or mimicking the activity of these miRNAs could suppress ZKSCAN3 expression and alleviate its contribution to tumorigenesis." (PMID 39519085, 2024). "The ZKSCAN3 upregulation in various cancers could be attributed to this gene amplification." (PMID 36012568, 2022). "Furthermore, despite the severe impact on fork structure and chromosomal stability, depletion of ZKSCAN3 did not affect the short-term survival of BRCA1-proficient or BRCA1-deficient cells after treatment with cancer drugs hydroxyurea, PARPi, or cisplatin." (PMID 35779634, 2022).
cancer (continued). "However, existing evidence suggests ZKSCAN3 may function in cancer." (PMID 41393507, 2025). "Overall, ZKSCAN3 was immunoreactive in 51 (34%) of 150 benign, 92 (63%) of 146 high-grade PIN (HGPIN), and 279 (93%) of 300 carcinoma tissues." (PMID 32824199, 2020). "The focus of this study is on cancer and non-cancer cells and the differences in ZKSCAN3 KO in these two cell types." (PMID 37175493, 2023). "Zinc finger with KRAB and SCAN domains 3 (ZKSCAN3), which belongs to a family of zinc finger transcription factors, is reported to be a master transcriptional repressor of autophagy in human cancer cells." (PMID 37175493, 2023). "ZKSCAN3 overexpression in advanced cancers can be explained by an increase in gene copy variation; however, this model does not apply to early cancer precursor lesions or some advanced cancers without increased copy number." (PMID 36012568, 2022). "All 67 tissues with paired samples available showed exceedingly stronger expression of ZKSCAN3 in cancer than in the non-neoplastic cervical mucosa." (PMID 30241382, 2018). "Overall, 67 specimens had non-neoplastic cervical mucosa adjacent to cancer tissues for comparison, and 45 of these specimens (67%) showed weaker nuclear expression of ZKSCAN3 at the squamous epithelial cells, especially at the basal layer." (PMID 30241382, 2018). "To further rule out whether the results were inconsistent due to different cell types, we generated ZKSCAN3 KO HK-2 (non-cancer) cells and Hela (cancer) cells via the CRISPR/Cas9 system." (PMID 37175493, 2023). "Next, to compare the expression grade, as well as expression frequency between cancer and non-neoplastic mucosa, we measured the scores of ZKSCAN3 expression based on both the intensity and proportion of expression, which were compared between CC tissues and non-neoplastic cervical mucosae." (PMID 30241382, 2018). "Another study found that the function of ZKSCAN3 in human cells is more inclined to cancer-related pathway regulation rather than directly mediating autophagy or lysosomal generation, and its mechanism of action may be closely related to the cell type and the mode of gene intervention." (PMID 40723888, 2025). "We found that ZKSCAN3 may be a cancer-related gene involved in cancer progression, but not an essential transcriptional repressor of autophagic or lysosomal genes, as the lacking of ZKSCAN3 cannot significantly promote the expression of autophagic and lysosomal genes." (PMID 37175493, 2023). "In contrast, aberrantly high expression of ZKSCAN3 was observed in dysplastic adenomas without ZKSCAN3 gene amplification, suggesting that ZKSCAN3 could play a role in both early carcinogenic processes and cancer progression." (PMID 36012568, 2022).
bacterial infection (1 paper, 2023). "We investigated ZKSCAN3 levels in response to bacterial infection and found that ZKSCAN3 protein is increased by exposure to P. aeruginosa." (PMID 37144628, 2023).
metabolic disorders (1 paper, 2025). "Within metabolic disorders, including T2DM-AS, high-glucose stress activates ZKSCAN3, leading to its nuclear retention and subsequent inhibition of macrophage autophagy, which accelerates atherosclerotic plaque formation." (PMID 40723888, 2025).